MBD5 (methyl-CpG binding domain protein 5)
Description:
Non-catalytic component of the polycomb repressive deubiquitinase (PR-DUB) complex, a complex that specifically mediates deubiquitination of histone H2A monoubiquitinated at 'Lys-120' (H2AK119ub1). Important for stability of PR-DUB components and stimulating its ubiquitinase activity. As part of the PR-DUB complex, associates with chromatin enriched in histone marks H3K4me1, H3K4me3, and H3K27Ac, but not in H3K27me3. The PR-DUB complex is an epigenetic regulator of gene expression, including genes involved in cell growth and survivability. MBD5 and MBD6 containing complexes associate with distinct chromatin regions enriched in genes involved in different pathways. Heterochromatin recruitment is not mediated by DNA methylation. The PR-DUB complex is an epigenetic regulator of gene expression, including genes involved in development, cell communication, signaling, cell proliferation and cell viability.
Synonyms: KIAA1461; FLJ11113; C2DELq23.1; DEL2Q23.1; MRD1
Tractability: No criterion of Open Targets' tractability assessment is met for any kind of drug.
Gene: Protein-coding gene on chromosome 2 (148,021,011 to 148,516,971, forward strand). Ensembl gene ENSG00000204406.
Subcellular location: Nucleus (Isoform 1); Chromosome; Nucleus (Isoform 2)
Subcellular location (Human Protein Atlas): Nucleoplasm; Midbody
Pathways (Reactome):
Metabolism of proteins: UCH proteinases
Gene Ontology:
Molecular function: chromatin binding; DNA binding
Biological process: nervous system development; regulation of behavior; glucose homeostasis; positive regulation of growth hormone receptor signaling pathway; regulation of multicellular organism growth; regulation of multicellular organismal process
Cellular component: chromocenter; chromosome; extracellular exosome; nucleoplasm; nucleus
Genetic constraint (gnomAD): Loss-of-function variants: 11 observed, 112.85 expected, observed/expected ratio (o/e) 0.0975, 90% interval 0.06 to 0.16. The upper end of that interval is the gene's LOEUF score, 0.16, which puts it in group 1 of 6, group 1 being the genes least tolerant of losing a copy. Missense variants: 1,834 observed, 2,133.3 expected, observed/expected ratio (o/e) 0.86, 90% interval 0.83 to 0.89. Synonymous variants: 705 observed, 781.66 expected, observed/expected ratio (o/e) 0.9, 90% interval 0.85 to 0.96.
Gene-disease validity (ClinGen):
ClinGen rates the evidence that MBD5 causes each of these diseases.
complex neurodevelopmental disorder (autosomal dominant): Definitive. A disorder that involves more than one phenotype associated with the central nervous system, including but not limited to intellectual disability, autism, and seizures (epilepsy).
Homologues: Orthologues: chimpanzee MBD5 (99% identical), macaque MBD5 (99% identical), rabbit MBD5 (98% identical), dog MBD5 (98% identical), pig MBD5 (98% identical), rat Mbd5 (94% identical), guinea pig MBD5 (93% identical), mouse Mbd5 (82% identical), tropical clawed frog mbd5 (64% identical), zebrafish mbd5 (25% identical), Drosophila melanogaster sba (16% identical). Paralogues in human: MBD6 (16% identical).
Diseases named in the same sentence as MBD5 in open-access papers:
MBD5 is named in the same sentence as 46 diseases in open-access papers, as found by Europe PMC text mining. Sharing a sentence is not in itself a finding about the gene and the disease. The quoted sentences say what the papers report.
Intellectual disability (18 papers, 2010 to 2025). "We identified a novel variant in MBD5 located within intron 6: c.114‐13A>G (NM_018328.5) in a family with a patient presenting intellectual disability." (PMID 40662461, 2025). "The MBD5 gene, located in the q23.1 region of chromosome 2 in the human genome, is essential for nervous system development and is linked to intellectual disability." (PMID 40662461, 2025). "The most prevalent mutation is MBD5 haploinsufficiency, which is linked to syndromes that include microcephaly, intellectual disability, severe speech impairments, and epileptic seizures." (PMID 40662461, 2025). "Disruptions in the MBD5 gene have been linked with an array of clinical features such as global developmental delay, intellectual disability, autistic-like symptoms, and seizures, through unclear mechanisms." (PMID 37628781, 2023). "Haploinsufficiency of MBD5 causes neurodevelopmental disorders such as intellectual disability, autism spectrum disorders, and seizures." (PMID 34659328, 2021). "This region contains the MBD5 gene, whose deletion has been associated with intellectual disability, seizures, significant speech impairment, and behavioral problems." (PMID 33584783, 2020). "Disruptions in the MBD5 gene, such as deletions and duplications, have been linked with NDDs, and the development of an array of clinical features such as global psychomotor delay, intellectual disability, autistic-like symptoms and seizures." (PMID 37628781, 2023). "Indeed, Mbd5, up-regulated in our datasets, is responsible for the correct neurite outgrowth and its deletion causes intellectual disability." (PMID 35645710, 2022). "Based on the presence of the MBD and PWWP domains in the encoded protein and the association of MBD5 mutation with human mental retardation, we hypothesized that MBD5 plays a unique role during development." (PMID 23077600, 2012). "It is unknown whether MBD5 or MBD6 also bind methylated DNA; this question has interest for basic research, but also practical consequences for human health, as MBD5 deletions are the likely cause of certain cases of mental retardation." (PMID 20700456, 2010). "Haploinsufficiency of the MBD5 gene can result in syndromes characterized by microcephaly, intellectual disability, severe speech disorders, and epileptic seizures." (PMID 40662461, 2025). "Chromosome 2q13.1 deletion most likely leads to autism and intellectual disability because MBD5 (methyl CpG binding domain protein 5) is deleted." (PMID 30542652, 2018). "First, a microdeletion of the MBD5 gene has recently been shown to correlate with mental retardation in 8 human patients." (PMID 20700456, 2010). "FOXP1 and MBD5 gene mutations were associated with EMA complicated with mental retardation, and MBD5 gene mutations were associated with non-convulsive status epilepticus." (PMID 40380288, 2025). "First, microdeletions of the MBD5 gene were detected in 65 patients with mental retardation." (PMID 23077600, 2012). "The MBD5 gene within the 2q23.1 deletion has been shown to be the primary gene responsible for neurological features of ASD, seizures, and intellectual disability." (PMID 24885232, 2014).
epilepsy (9 papers, 2012 to 2025). A brain disorder characterized by episodes of abnormally increased neuronal discharge resulting in transient episodes of sensory or motor neurological dysfunction, or psychic dysfunction. "Haploinsufficiency of MBD5 causes diverse phenotypes which include hyperphagia, behavioural problems, craniofacial abnormalities, language impairment, microcephaly, development and motor delay, short stature, sleep disturbance, epilepsy, hyperphagia, obesity, and seizures." (PMID 38297031, 2024). "MBD5, a transcriptional regulator is implicated in ID, ASD, epilepsy and specific cognitive impairments." (PMID 39849619, 2025). "MBD5 in humans is mutated in multiple diseases ranging from autism spectrum disorders (ASD), epilepsy, to dementia." (PMID 38366571, 2024). "Regarding the etiology of epilepsy, five (11.1%) were genetic, including one with SCN2A mutation, one with KCNA2 mutation, one with MBD5 mutation, one with WFS1 mutation, and one with OCRL mutation." (PMID 38419715, 2024).
autism spectrum disorder (8 papers, 2012 to 2025). A spectrum of developmental disorders that includes autism, and Asperger syndrome. "Mutations in the MBD5 gene are typically associated with neurodevelopmental disorders, traits of autism spectrum disorder, and cognitive impairments." (PMID 40662461, 2025). "De novo missense and protein-truncating variants from exome sequencing studies have directly implicated MBD5 in the etiology of autism spectrum disorder (ASD) and related neurodevelopmental disorders (NDDs)." (PMID 32503625, 2020). "Missense variants in MBD5 (which perhaps have reduced penetrance) are associated with risk of autism spectrum disorders and may also contribute to schizophrenia and depression." (PMID 38297031, 2024). "In addition to large copy number variants (CNVs), de novo missense and protein-truncating variants from exome sequencing studies have also directly implicated MBD5 in the etiology of autism spectrum disorder (ASD) and related neurodevelopmental disorders (NDDs)." (PMID 32503625, 2020).
developmental delay (7 papers, 2014 to 2024). "In this study, we describe a rare genetic variant in MBD5 (NM_018328.4)—c.2297del (p.(Thr766Ilefs*18)), the only reported case in Portugal, from a 12-year-old female presenting Rett-like phenotype, developmental delay, and drug-resistant seizures." (PMID 37628781, 2023). "First, we describe the clinical history of a 12-year-old child harboring a novel MBD5 rare variant, presenting developmental delay, seizures, and Rett-like stereotyped hand movements." (PMID 37628781, 2023). "MBD5 variants are often associated with neurological symptoms, including psychomotor developmental delays and seizures." (PMID 37628781, 2023). "Despite genetic evidence implicating MBD5 as the only overlapping gene between various 2q23.1 microdeletions, the function of MBD5 and its causality to 2q23.1 microdeletion syndrome, a disorder characterized by developmental delay and autistic features, has yet to be determined." (PMID 25001217, 2014). "The parent with an MBD5 deletion in an apparently nonmosaic form has a psychiatric disorder in the absence of developmental delay or dysmorphism." (PMID 28944244, 2017). "She did not present other MBD5-related neurodevelopmental symptoms such as developmental delay, speech impairment, seizure, and abnormal behaviors, suggesting other factors may modify the clinical presentations of the MBD5-haploinsufficiency." (PMID 34659328, 2021).
Kleefstra syndrome (6 papers, 2014 to 2025). A genetic disorder characterized by intellectual disability, childhood hypotonia, severe expressive speech delay and a distinctive facial appearance with a spectrum of additional clinical features. "Autosomal Dominant Mental Retardation 1/2q23.1 deletion syndrome, caused by pathogenic MBD5 variants, shares several phenotypic traits with Kleefstra syndrome." (PMID 36551904, 2022). "In addition, pathogenic de novo variants in MBD5 and in other epigenetic regulators (SMARCB1, NR1I3, KMT2C) were reported in individuals with a clinical diagnosis of Kleefstra syndrome (KS; OMIM #610253)." (PMID 35205380, 2022). "In addition to EHMT1 mutations, de novo variants were reported in four additional genes (MBD5, SMARCB1, NR1I3, and KMT2C), in single individuals with clinical characteristics overlapping Kleefstra syndrome." (PMID 29069077, 2017).
Rett syndrome (6 papers, 2014 to 2024). A severe neurodevelopmental disorder affecting the central nervous system. "In an analogous manner to what is observed in Rett syndrome, it is possible that the ciliary defects observed can be induced by the transcriptional functions of MBD5." (PMID 37628781, 2023). "These disorders include Pitt-Hopkins syndrome, Smith-Magenis syndrome, Rett syndrome, MBD5 deletion/duplication, and Angelman syndrome." (PMID 29069077, 2017). "Indeed, several chromatin-related disorders, such as Pitt-Hopkins syndrome, Smith-Magenis syndrome, Rett syndrome, MBD5 deletion/duplication, and Angelman syndrome, have a clear clinical overlap characterized by ID/ASD and additional behavioral and neurological problems." (PMID 29069077, 2017).
microcephaly (4 papers, 2020 to 2025). A congenital or acquired developmental disorder in which the circumference of the head is smaller than normal for the person's age and sex. "The majority (~84%) of the phenotypes of 2q23.1 deletion syndrome are caused by haploinsufficiency of MBD5, and these commonly include ID, developmental delay, severe speech impairment, seizures, motor delay, sleep disturbances, autistic behaviours, microcephaly and subtle dysmorphic features." (PMID 36547251, 2022). "Indeed, MBD5-specific disruptions do not present with microcephaly and sleep disturbances in contrast to larger 2q23.1 deletions." (PMID 36547251, 2022).
schizophrenia (4 papers, 2013 to 2024). A major psychotic disorder characterized by abnormalities in the perception or expression of reality. "New research shows that chromosomal abnormalities of MBD5 is associated with autism and schizophrenia." (PMID 23825544, 2013). "Furthermore, patients with haploinsufficiency of MBD5 may present with psychiatric disorders, including anxiety, bipolar disorder, and schizophrenia, suggesting the variable expressivity of MBD5 haploinsufficiency." (PMID 34659328, 2021).
Angelman syndrome (3 papers, 2010 to 2021). A neurogenetic disorder characterized by severe intellectual deficit and distinct facial dysmorphic features. "Recently several patients with 2q23.1 microdeletions encompassing the methyl binding domain gene MBD5 and a clinical and behavioural phenotype reminiscent of Angelman syndrome were reported." (PMID 20459762, 2010).
Anxiety (3 papers, 2014 to 2022). Intense feelings of nervousness, tension, or panic often arise in response to interpersonal stresses. "On the one hand, a group of lines including Cdkl5−/y, Il1rapl1−/y, Ptchd1−/y, Atp6ap2Camk2a/y, Mbd5+/−, and Ehmt1+/− displayed alterations mainly in activity, repetitive behaviour, novelty exploration and anxiety (Axis 1)." (PMID 36551904, 2022). "Novel environment-induced activity and anxiety were tested to further characterize the neurobehavioral phenotype of Mbd5+/GT mice." (PMID 25001218, 2014).
Autosomal Dominant Mental Retardation 1 (3 papers, 2018 to 2022). "MBD5, also referred to as mental retardation autosomal dominant 1 and now given the name MBD5-Associated Neurodevelopmental Disorder (MAND), was originally described in the context of the 2q23.1 microdeletion syndrome thought to be an Angelman Syndrome mimic." (PMID 29801487, 2018).
Obesity (3 papers, 2012 to 2024). Accumulation of substantial excess body fat. "Mouse model of conditional knockout of Mbd5 in liver or adipose tissues will be needed to elucidate the relationship between Mbd5 and obesity associated insulin resistance." (PMID 23077600, 2012).
Cognitive impairment (2 papers, 2014 to 2025). Abnormal cognition is characterized by deficits in thinking, reasoning, or remembering. "Our study indicates that the Mbd5+/GT mouse model recapitulates most of the hallmark phenotypes observed in 2q23.1 deletion carriers including abnormal social behavior, cognitive impairment, and motor and craniofacial abnormalities." (PMID 25001218, 2014).
epileptic encephalopathies (2 papers, 2014 to 2023). "When the patient was seven years old, next-generation sequencing (NGS), sequencing of 228 genes related to epileptic encephalopathies was performed, identifying a heterozygous mutation in the MBD5 gene." (PMID 37628781, 2023). "Recently, a deleterious mutation in MBD5 was found in a patient with epileptic encephalopathy." (PMID 24885232, 2014). "Together with our study, these results support a conclusion that MBD5 and HNRNPU play an important role in the susceptibility to IS and epileptic encephalopathy." (PMID 24885232, 2014). "The CNV loss at 2q23.1 includes MBD5, a methyl-DNA binding protein that is a causative gene of ASD and a candidate gene for epileptic encephalopathy." (PMID 24885232, 2014).
Hypoglycemia (2 papers, 2012 to 2017). A decreased concentration of glucose in the blood. "Overall, the elevated insulin sensitivity in dwarf Mbd5-deficient mice might contribute to the alteration of glucose homeostasis, resulting in hypoglycemia." (PMID 23077600, 2012). "A study conducted on MBD5 knockout mice revealed severe growth retardation and persistent hypoglycemia, hypoinsulinemia, enhanced glucose intolerance and elevated insulin sensitivity." (PMID 28604785, 2017).
Smith-Magenis syndrome (2 papers, 2015 to 2017). Smith-Magenis syndrome (SMS) is a complex genetic disorder characterized by variable intellectual deficit, sleep disturbance, craniofacial and skeletal anomalies, psychiatric disorders, and speech and motor delay. "As an example, we show that when MBD5 and RAI1 are both haploinsufficient they share common perturbed pathways that likely contribute to the overlapping phenotypes exhibited by 2q23.1 deletion syndrome and Smith-Magenis syndrome patients." (PMID 25853262, 2015).
colitis (1 paper, 2019). Inflammation of the colon. "Gut-specific conditional deletion of mbd3 mice showed a large increase in proliferating cells in the colon after DSS treatment compared to control animals, markedly increased susceptibility to colitis-induced tumorigenesis via c-Jun-MBD5/NuRD-AP-1 signaling." (PMID 31998373, 2019).
infantile spasms (1 paper, 2014). A rare epilepsy syndrome characterized by onset of epileptic spasms in infants between 2 and 12 months of age, and rarely up to 24 months. "The finding of MBD5 in both ASD and IS also offers the opportunity to dissect the shared molecular pathophysiology between ASD and infantile spasms." (PMID 24885232, 2014).
Lennox-Gastaut syndrome (1 paper, 2017). Lennox-Gastaut syndrome (LGS) belongs to the group of severe childhood epileptic encephalopathies. "Similarly, the c.1885 A>G variant in MBD5 in a boy (D1471) with Lennox-Gastaut Syndrome (LGS) was inherited from his mother who was reported to have possible febrile seizure during childhood." (PMID 28074849, 2017).
lung carcinoma (1 paper, 2022). "Consistently, genome-wide CRISPR screenings by DepMap across different lung cancer types revealed that lung cancer cells are generally more sensitive to MBD6 depletion, while MBD5 is not essential for lung cancer cell viability." (PMID 36180891, 2022).
memory (1 paper, 2014). The activities involved in the mental information processing system that receives (registers), modifies, stores, and retrieves informational stimuli. "Taken together, these data show that Mbd5 haploinsufficiency in mice leads to behavioral and learning and memory impairments accompanied by functional deficits in cortical neurons, providing an experimental model for social disturbances and ID in patients with 2q21.3." (PMID 25001218, 2014).
mental disorder (1 paper, 2010). A disease that has its basis in the disruption of mental process. "MBD5 is expressed in the human brain, and several lines of evidence link MBD5 mutations with mental disorders." (PMID 20700456, 2010).